PNPLA3 (patatin like domain 3, 1-acylglycerol-3-phosphate O-acyltransferase )
Diseases named in the same sentence as PNPLA3 in open-access papers (continued):
Sharing a sentence is not in itself a finding about the gene and the disease.
chronic hepatitis C (24 papers, 2011 to 2026). "In conclusion, IL28B and PNPLA3 genotypes are associated with rapid fibrosis progression in patients with chronic hepatitis C. The FPR score identifies HCV patients who has a high risk of fibrosis progression and require urgent antiviral treatment." (PMID 26352693, 2015). "Two recent studies from Italy reported strong effects of the PNPLA3 148M variant also on the risk of HCC in chronic hepatitis C, while a third Italian study suggested that this allele was predominantly associated with metabolic cirrhosis." (PMID 22087248, 2011). "In conclusion, serum AFP level is an important factor in predicting HCC development after the antiviral therapy for Japanese patients with chronic hepatitis C, the mechanism of which might involve its significant associations with the SNP genotype of PNPLA3." (PMID 23772356, 2013). "Serum AFP level is an important factor in predicting HCC development after the antiviral therapy for Japanese patients with chronic hepatitis C, the mechanism of which might involve its significant associations with the SNP genotype of PNPLA3." (PMID 23772356, 2013). "This study aims to investigate the association of three intronic PNPLA3 polymorphisms (rs4823173, rs2896019, and rs2281135) with liver injury in HCV-infected patients with spontaneous HCV clearance (SC) and chronic hepatitis C (CHC)." (PMID 41516346, 2026). "The PNPLA3 CC, CG, and GG genotype frequencies in chronic hepatitis C patients were 51.4%, 41.2%, and 7.4%, respectively." (PMID 33622266, 2021). "The present study included the largest sample of Brazilians with chronic hepatitis C assessed for the TM6SF2 and PNPLA3 polymorphisms to date." (PMID 33622266, 2021). "The aim of this study was to estimate the effect size of homozygosity for the PNPLA3 I148M variant (148M/M) on the fibrosis progression rate (FPR) and the interaction with age at infection in chronic hepatitis C (CHC)." (PMID 25171251, 2014). "Genetic variants including PNPLA3-rs738409 C>G, TM6SF2-rs58542926 C>T, MBOAT7-rs641738 C>T, and HSD17B13-rs72613567 T>TA have been shown to influence progression to advanced chronic liver disease (ACLD) in patients with chronic hepatitis C (CHC)." (PMID 33917196, 2021). "Our results obtained by analysis of paired biopsy specimens provide robust evidence to support the role of the PNPLA3 genotype in fibrosis progression and warrant further studies to explore the mechanistic role of PNPLA3 in fibrosis progression in patients with chronic hepatitis C." (PMID 26352693, 2015). "Through analysis of long-term data, we demonstrated that genotypes of IL28B and PNPLA3 are independent predictors of rapid fibrosis progression in patients with chronic hepatitis C who failed to achieve SVR following interferon-based therapy." (PMID 26352693, 2015).
liver cirrhosis (24 papers, 2014 to 2025). "Carrying at least one allele G of PNPLA3 increased the risk of liver cirrhosis (OR 1.48; 95% CI 1.36–1.99)." (PMID 41004464, 2025). "We assessed the effect of T2D and PNPLA3 rs738409 polymorphism on liver cirrhosis among Taiwan Biobank (TWB) participants." (PMID 35330730, 2022). "PNPLA3 has not only been associated with the development of liver cirrhosis and HCC, but has also shown a stronger association when compared with other risk alleles (e.g., SERPINA1, TM6SF2, MBOAT7 or GCKR)." (PMID 33804385, 2021). "In the ALD cohort, association of liver cirrhosis remained significant also after further adjusting for risk variants of other well-established ALD genetic modifiers (PNPLA3, TM6SF2 and MBOAT7)." (PMID 34638908, 2021). "TaqMan genotyping assay was used to investigate the association of two PNPLA3 SNPs (rs738409 and rs2281135) with the risk of liver cirrhosis." (PMID 25337145, 2014). "This study indicates that Taiwanese adults with T2D who have the PNPLA3 rs738409GG genotype might have a higher risk for liver cirrhosis than those with the CC genotype." (PMID 35330730, 2022). "Association of liver cirrhosis with PNPLA3 rs738409 and T2D." (PMID 35330730, 2022). "In a recessive model, the presence of the PNPLA3 GG genotype was markedly associated with a greater likelihood for liver cirrhosis development (OR 95%CI = 4.03 (1.93–8.41), p = 8.4 × 10−5), and significant associations were also found in dominant, codominant and log additive models." (PMID 34640639, 2021). "These patients may benefit from a genetic screening for PNPLA3 mutation, to identify those with a more aggressive disease and at higher risk of progression to liver cirrhosis." (PMID 33713286, 2021). "This study aimed to investigate whether PNPLA3 polymorphisms are a risk factor for liver cirrhosis in a Chinese Han population with chronic hepatitis B (CHB)." (PMID 25337145, 2014). "Our group of liver transplant candidates with liver cirrhosis of various aetiologies showed a significantly higher prevalence of unfavourable variants in the two studied genes, SERPINA1 and PNPLA3." (PMID 41004464, 2025). "Individuals with PNPLA3 CG and GG genotypes were more frequently observed not only in these two subgroups but also among patients with virus-related liver cirrhosis." (PMID 41004464, 2025). "There is a need for further research into the role of T2D and PNPLA3 rs738409 in the development of liver cirrhosis." (PMID 35330730, 2022). "The individual risks for liver cirrhosis caused by NASH and alcohol are largely determined by genetic risk factors, with polymorphisms in PNPLA3 and TM6SF2 and also MBOAT7, HSD17B13 and PCKS7 being the major common genetic determinants." (PMID 34360999, 2021). "Genetic factors are involved in the development of liver cirrhosis and we found a correlation between increased APRI scores and 2 risk alleles of PNPLA3 SNPs in the CCHC." (PMID 26950933, 2016). "PNPLA3 is the strongest and the most replicated genetic risk for both alcohol- and non-alcohol-associated liver cirrhosis as reported in genome-wide association studies." (PMID 37887024, 2023). "PNPLA3 (I148M) variant is likely to hasten the progression to liver cirrhosis, but they appear to have no role in predicting the occurrence of HCC." (PMID 34711009, 2021). "The present study aimed to determine whether PNPLA3 polymorphisms (rs738409 and rs2281135) have an adverse influence on HBV-related liver cirrhosis in a Chinese Han population." (PMID 25337145, 2014). "The lack of association of the PNPLA3 variant with liver cirrhosis in the PBC cohort indicates that the skin might be the major site where the antipruritic effects are exerted." (PMID 25297933, 2014). "However, this study cannot completely rule out the possible association of PNPLA3 SNPs with to HBV infection-related liver cirrhosis." (PMID 25337145, 2014).
liver cirrhosis (continued). "There are strong genetic determinants in the development of ALD, e.g., PNPLA3, TM6SF2, and only approximately 10–20% of alcoholics develop cirrhosis of the liver." (PMID 34360999, 2021). "PNPLA3 and TM6SF2 genotypes in patients with and without liver cirrhosis." (PMID 30161167, 2018).
liver cancer (22 papers, 2011 to 2025). An epithelial or non-epithelial malignant neoplasm that arises from the liver. "Positioned within the PNPLA3 gene, rs3747207, although unrelated to liver cancer susceptibility, is significantly correlated with the severity and activity score (NAS) of NAFLD." (PMID 38395962, 2024). "We highlight the utility of this population-specific PNPLA3 genetic variant for genetic association studies and for the early prognosis and treatment of liver cancer." (PMID 38224715, 2023). "The main finding of the present study is the demonstration that specific variants of HSD17B13 and PNPLA3 genes interplay in the determination of genetic predisposition to chronic liver disease progression and liver cancer in HCV-infected subjects." (PMID 32382265, 2020). "The frequency of the PNPLA3 148M allele was increased both in alcohol-induced cirrhosis (OR = 1.92; 95%-CI: 1.28–2.86; p<0.002) and alcohol-associated liver cancer (OR = 4.37; 95%-CI: 2.97–6.43; p<0.001) as compared to healthy controls." (PMID 22087248, 2011). "Two variants, rs2294915 and rs2896019, encoded by the PNPLA3 gene, were found to be highly expressed in the liver tissue, as well as in the skin, cell-cultured fibroblasts, and adipose-subcutaneous tissue, all of which contribute to the risk of liver cancer." (PMID 38224715, 2023). "Mechanisms for the progression of NAFLD/NASH to liver cancer remain incompletely understood, pathogenesis could involve DNA damage of other loci, inflammatory response, genetic modifiers as PNPLA3 or TM6SF2 or mutations such as the recently reported ACVR2A mutations." (PMID 36587184, 2022). "The PNPLA3 I148M variant, carried by over a third of NASH patients, is associated with NASH progression, liver cancer, and higher mortality." (PMID 34879108, 2021). "The PNPLA3 risk variant was associated with higher MELD (P = 0.02) in treated patients, whereas MBOAT7 increased the odds for liver cancer (OR = 3.71)." (PMID 34949757, 2021). "The SNPs in PNPLA3 and VDR genes, associated to the development of chronic liver disease and progression towards liver cancer, have been characterized in 258 healthy unrelated male volunteers." (PMID 26219465, 2015). "Other mutations such as rs738409-G (PNPLA3) and rs1800562-A (HFE) could also influence the observed association between serum cholesterol and liver cancer." (PMID 33808094, 2021). "In our HCV-infected patients PNPLA3 148M/M homozygosity revealed an odds ratio of 1.666 for the risk of liver cancer, which failed to reach statistical significance with our sample size." (PMID 22087248, 2011). "Furthermore, the previous Japanese report indicated that the PNPLA3 GG type might affect development of liver-related events, including liver cancer." (PMID 34798835, 2021). "Besides environmental, behavioral, viral and metabolic factors, genetic polymorphisms in patatin-like phospholipase-3 (PNPLA3) and vitamin D receptor (VDR) genes have been related to the development of chronic liver disease and progression towards liver cancer." (PMID 26219465, 2015). "At the 22q region, PNPLA3 incorporate mostly in the phospholipid metabolism and lipase activity pathways, SAMM50 enriched in the mitochondrial assembly pathway (GO cellular components), and PARVB enriched in the liver cancer pathway." (PMID 31311600, 2019).
alcoholic cirrhosis (15 papers, 2011 to 2024). "MARC1 and PNPLA3, genes implicated by GWAS in alcohol cirrhosis, show to correlate with lipid droplet-associated and mitochondria-mediated oxidative damage in AC iHLCs." (PMID 38693144, 2024). "In European Caucasians, the PNPLA3 rs738409 variant was associated with alcoholic liver cirrhosis and elevated aminotransferase levels." (PMID 30513996, 2018). "This approach had enough statistical power as to correctly identify and confirm the known dominant effect of the PNPLA3 rs738409 variant in our disease control group of patients with alcoholic cirrhosis." (PMID 28594920, 2017). "Multivariate analysis confirmed the CXCL1 rs4074 risk variant as independent risk factor for alcoholic liver cirrhosis in addition to age, gender and the PNPLA3 148M risk variant." (PMID 24260493, 2013). "To check if carriage of the CXCL1 rs4047 A allele is an independent risk factor for alcoholic cirrhosis when other known risk factors such as age, gender, and the PNPLA3 rs738409 risk variant were also taken into account, we calculated a Cox regression model." (PMID 24260493, 2013). "This point was clearly demonstrated also by the recent study that investigated the role of Genotype PNPLA3 rs738409(GG) which is associated with alcoholic liver cirrhosis in alcoholic Caucasians of German ancestry." (PMID 22530132, 2012). "Genotype data of PNPLA3 variant rs738409 in German (n = 128) and Dutch (n = 7) patients with alcoholic liver cirrhosis, German patients with idiopathic and hereditary CP and in German controls." (PMID 22276112, 2012). "Finally, the HSD17B13 rs72613567 variant, in addition to the PNPLA3 rs738409 variant, also allows good accuracy of the prognostic score for the future development of alcoholic cirrhosis to be achieved based on the age of onset of at-risk alcohol consumption." (PMID 37626629, 2023). "Furthermore, age, gender and PNPLA3 risk variant were confirmed as risk factors for alcoholic cirrhosis." (PMID 24260493, 2013). "However, a common PNPLA3 variant (p.I148M) is associated with the development of alcoholic liver cirrhosis (ALC)." (PMID 22276112, 2012). "However, rs738409 in PNPLA3 is strongly associated with alcoholic cirrhosis in Mestizo subjects." (PMID 25337145, 2014). "Thus, it may be increased hepatic inflammatory activity and fibrosis in response to lipid accumulation, which is associated with the PNPLA3 148M variant that enhances the risk for HCC in alcoholic cirrhosis." (PMID 22087248, 2011). "Accurate alcohol history and the addition of genetic testing for PNPLA3 rs738409 and HSD17B13 rs72613567 variants allow our models to increase diagnostic accuracy for compensated alcoholic cirrhosis, with low additional costs." (PMID 37626629, 2023). "We previously developed a prognostic model of future development of alcoholic cirrhosis in males that took into account BMI and the PNPLA3 rs738409 and cluster of differentiation 14 (CD14) rs2569190 variants." (PMID 37626629, 2023). "Most recently, an allele of patatin-like phospholipase domain-containing protein 3 (PNPLA3 I148M), a triglyceride-degrading enzyme, was identified as an independent risk factor for alcoholic cirrhosis." (PMID 28988570, 2017). "Homozygous PNPLA3 148M/M genotype (OR 2.83; 95%-CI: 1.24–6.42; p = 0.013) was confirmed as a risk factor of HCC in alcoholic cirrhosis." (PMID 22087248, 2011). "The combined effect of PNPLA3 and TM6SF2 genetic variants may predispose to a worsening risk to develop HCC in alcoholic cirrhosis." (PMID 30513996, 2018). "The absence of an association of PNPLA3 p.I148M with alcoholic CP seems not to point to a common pathway in the development of alcoholic CP and alcoholic liver cirrhosis." (PMID 22276112, 2012). "In addition, the rs738409 variant was identified as an independent predictor of HCC occurrence pointing out for the first time a role of the I148M PNPLA3 variant in the risk of HCC (OR = 1.76; p < 0.05) also in non-drinking alcoholic cirrhosis." (PMID 30513996, 2018).
coronary artery disease (13 papers, 2019 to 2025). "The PNPLA3 I148M variant correlates to only a small reduction in ischemic heart disease risk but was strongly associated with liver-related and all-cause mortality." (PMID 36035124, 2022). "A Mendelian randomisation analysis on a large Danish general population cohort confirmed a causal association between liver fat and ischemic heart disease (IHD) but demonstrated that carrying the PNPLA3 rs738409 C > G variant was associated with a better cardiovascular outcome in terms of IHD." (PMID 39412170, 2025). "PNPLA3 is predominantly expressed in hepatocytes and hepatic stellate cells, exhibiting hydrolytic activity against triglycerides (TGs) and retinol, thereby mitigating the risk of coronary heart disease." (PMID 38523778, 2024). "Analysis of data from 48 genome‐wide association studies including 60 801 cases with coronary artery disease (CAD) and 123 504 controls showed that the PNPLA3 rs738409 G allele was associated with a lower risk of CAD in a recessive adjusted model." (PMID 39412170, 2025). "Later, based on a Mendelian randomized approach, which proposed that PNPLA3 I148M does not causally conduce to ischemic heart disease, genetic variability in PNPLA3 appeared to be cleared from the notorious frame of exacerbating chronic liver diseases." (PMID 36403577, 2023).
atherosclerosis (10 papers, 2013 to 2026). A disease characterized by the build-up of fatty material and calcium deposition in the arterial wall resulting in partial or complete occlusion of the arterial lumen. "Given the dietary patterns among Mexican SC patients and the effect of PNPLA3 variants on atherosclerosis development, these patients should be followed to monitor the development of cardiometabolic disease." (PMID 41516346, 2026). "The association between the PNPLA3 SNP genotype and atherosclerosis in Italian NAFLD patients was previously reported." (PMID 31721770, 2019). "In a Sicilian cohort of biopsy-proven NAFLD patients, carotid atherosclerosis was independently associated not only with well-known risk factors for atherosclerosis, but also with the PNPLA3 GG genotype; this association was only observed in younger patients." (PMID 24069270, 2013). "The association of PNPLA3 GG genotype with atherosclerosis limited to younger patients is intriguing." (PMID 24069270, 2013). "Of note, this feature was validated in an independent cohort of Northern Italian NAFLD patients, where PNPLA3 GG genotype was also associated with atherosclerosis progression." (PMID 24069270, 2013). "Finally, the role of the rs738409 PNPLA3 polymorphism in atherosclerosis development is still uncertain." (PMID 36079710, 2022). "As for carotid IMT, which is a marker of early atherosclerosis and a validated predictor of CVD morbidity and mortality, our data show that subjects with the PNPLA3 G allele had lower IMT than patients with the CC genotype, being 0.78 mm vs. 1.00 mm respectively." (PMID 40244110, 2025). "Second there are racial differences in atherosclerosis and the PNPLA3 genotype." (PMID 31721770, 2019). "Although this study was merely observational and not designed to explore the reasons for the association of atherosclerosis markers with PNPLA3 genotype, some hypotheses can be proposed." (PMID 24069270, 2013). "Two studies on the association between the carotid intima-media thickness, a surrogate marker of subclinical atherosclerosis as is PWV, and the PNPLA3 SNP genotype in Italian NAFLD patients have been reported, but the findings were contradictory." (PMID 31721770, 2019). "Similarly, it has been confirmed in Japanese patients that the PNPLA3 is a susceptibility gene involved in the development and advancement of NAFLD, though its association with subclinical atherosclerosis has not been investigated." (PMID 31721770, 2019).
viral hepatitis (10 papers, 2012 to 2026). An acute or chronic inflammation of the liver parenchyma caused by viruses. "Well-characterized variants such as PNPLA3, TM6SF2, HSD17B13, and MBOAT7, along with less commonly studied loci and chromosomal alterations, are discussed in relation to major etiologies, including MASLD/MASH, viral hepatitis, alcohol-related liver disease, and autoimmune conditions." (PMID 41590522, 2026). "The adiponutrin (PNPLA3) p.I148M and transmembrane 6 superfamily member 2 (TM6SF2) p.E167K variants represent major genetic risk factors for progressive liver injury in nonalcoholic fatty liver disease (NAFLD), alcoholic liver disease (ALD) and chronic viral hepatitis." (PMID 30161167, 2018).
alcoholic fatty liver disease (9 papers, 2014 to 2023). Lipid infiltration of the hepatic parenchymal cells that is due to alcohol abuse. "PNPLA3(I148M) is strongly associated with NAFLD and alcoholic fatty liver disease in the population." (PMID 32170127, 2020).
central obesity (8 papers, 2013 to 2025). "Genomic (e.g., PNPLA3 polymorphism) and phenotypic (e.g., sarcopenic vs. central obesity phenotypes) stratification could optimize treatment selection, improving response rates and minimizing side effects." (PMID 41141254, 2025).